IL10 (interleukin 10)
Diseases named in the same sentence as IL10 in open-access papers (continued):
Sharing a sentence is not in itself a finding about the gene and the disease.
infection (continued). "Only the IL-10 and TNF-α transcripts showed a significant difference (P < 0.05) between both strains at the peak of infection (resp)." (PMID 24991553, 2014). "Infected DCs both expressed elevated IL-10 and were able to promote IL-10 expression in CD4 T cells, which constituted the largest population of IL-10-expressing cells in Cl13 infection at all time points observed." (PMID 24613988, 2014). "Relative to patients with silent infections, patients with severe infections had significantly higher levels of IL-17+CD4+ cells, decreased levels of IL-17+CD8+ cells, and higher levels of IFN-γ, IL-4, IL-10, and IFN-α2 (p < 0.001 for all comparisons)." (PMID 24646014, 2014). "In comparison to HSV-2 infected controls, the presence of 13 nm AgNPs at infection resulted in the significantly up-regulated production of IFN-γ, IL-10 and CCL2 (p≤0.05)." (PMID 25117537, 2014). "Overall, splenocytes of WT and p47phox−/− mice (± T. cruzi lysate) were activated early upon infection, as is evidenced by a significant increase in TNF-α, IFN-γ and IL-10 levels at day 7 pi." (PMID 25474113, 2014). "In the AP, the minor and severe infection groups had significantly higher levels of IFN-γ, IL-10, and IFN-α2 than the healthy control and silent infection groups." (PMID 24646014, 2014). "Cytokine production before infection showed that the plasmid expressing LdPxn1 antigen in the presence or absence of mGMCSF fusion induced the production of both IFN-γ and IL-10." (PMID 25500571, 2014). "There was a significant increase (p < 0.0001) in the amount of IL-10 produced by ALDCs and CD14+ cells in response to infection with MVA." (PMID 24890724, 2014). "Compared to initial counts at 1 day, the number of M. leprae remained relatively constant in B6 and IL-10−/− FP or decreased slightly in NOS2−/− and 10NOS2−/− FP at 4 months post infection." (PMID 25210773, 2014). "IL-10 was increased around week 5 post infection, while the stress cytokines IL-6 and MIP-1α were significantly increased late in infection." (PMID 25398130, 2014). "This study provided some basic data on the optimal time to observe different immune parameters, for example, IL-2+, IL-4+ CSCs stimulated about 12 days post infection, TNF-α, IFN-γ, IL-10 cytokines only transiently increased in the early infection." (PMID 24725777, 2014). "Having identified the cell types expressing IL-10 in response to Cl13 infection in vivo, we examined the relationship between LCMV infection and IL-10 expression." (PMID 24613988, 2014). "Compared with uninfected mice, infected wild-type mice showed higher levels of IL-4, IL-10 and IL-13, with similar levels of α-smooth muscle actin, galectin-3, TGF-β1, IL-17, IFN-γ, and lower IL-12 levels at 90 days post-infection." (PMID 25032961, 2014). "In comparison, splenocytes of infected/p47phox−/− mice (± TcL) exhibited a mixed response with a predominance of IL-10 (IL-10>TNF-α>IFN-γ) at 7, 14, 21 and 30 days post-infection." (PMID 25474113, 2014). "Using Gene Set Enrichment Analysis (GSEA), we found that canonical immune pathways, including JAK-STAT, NFAT, and IL10, were among the most significantly enriched gene sets up-regulated during type II:MAF1 infection relative to type II wild type." (PMID 24781109, 2014). "In human infections with the leprosy agent Mycobacterium leprae, type I IFN has also been shown to induce IL-10 and restrict IFN-γ–mediated antibacterial responses." (PMID 25187652, 2014). "Serum IL-6, IL-10, and IFNγ continued to increase during the clinical course; IP-10 and MCP-1 remained at a high level from the beginning of infection." (PMID 25003343, 2014). "In both models of infection, protection was correlated to parasite antigen-specific production of IFN-γ and down-regulation of parasite-mediated IL-4 and IL-10 responses." (PMID 24382098, 2014). "The anti-inflammatory cytokine IL-10 only increased on day 6 p.i in both AH1 and CK1 infection, but at a significantly lower level in CK1-infected mice (P<0.05)." (PMID 25232731, 2014).
infection (continued). "WNV H8912 induced constitutive IL-10 production, upregulation of IFN-β and IL-1β expression, and a specific IgM response on day 10 post-infection." (PMID 23785537, 2013). "Wild type (WT) and IL-10−/− C57BL/6 mice were used to characterize the role of IL-10 in the innate and adaptive immunity against Paracoccidioides brasiliensis (Pb) infection." (PMID 24205424, 2013). "Similar to what was observed in vivo, the in vitro data again demonstrated an altered immune response with exaggerated IL-10 and IFN-β secretion observed during infection of primed macrophages." (PMID 24009502, 2013). "Based on recent data about T reg expansion during infection, Foxp3 expressing CD4+CD25+ T cells were found responsible for TGF-β and CD4+CD25−Foxp3− T cells for IL-10 production." (PMID 23638195, 2013). "We found similar results with primary T cell lines from deer mice at 10 days post infection with SNV, in which Ifng, Il4, Il5, Il10 and Tgfb were elevated." (PMID 23570545, 2013). "Real-time PCR was used to determine the difference in proinflammatory cytokine production following infection with the four H1N1 viruses in the mouse lung, including IL-1, IL-10, MCP-1, TNF-α, IFN-γ." (PMID 23637827, 2013). "We also observed that treatment with IL-10 significantly inhibited the expression of TNF-α and IL-6 induced by infection." (PMID 24260222, 2013). "At eight weeks post infection, the percentages of CD4+ IFN-γ+ and of CD4+ IL-4+ T cells were also similar, whereas the percentage of CD4+ IL-10+ T cells was significantly lower in Linb-11-immunized mice." (PMID 23717705, 2013). "Apparently, the same cytokine profile, including IL-6, IL-8, IFN-γ, IL-10 and chemoattractants, exists in both porcine and human/NHP ZEBOV infection." (PMID 23626748, 2013). "Our studies showed that levels of IL-1, IL-10, MCP-1, TNF-α and IFN-γ following H1N1/144+177 infection were significantly higher compared with H1N1/WT virus, and H1N1/144 and H1N1/177 did not induce all of these cytokine up-regulation but two or three." (PMID 23637827, 2013). "When healthy controls and patients with infection were compared, IL2 and IL23 gene expression was lower in patients with infection, and gene expression of IL10 and IL27 were greater in patients with infection." (PMID 23935244, 2013). "During complicated infection, overly expressed TNF-α and IL-10 thus act to downregulates IL-6 production." (PMID 24324686, 2013). "Our results point to an increase that is dependent on the immune system and that was triggered by the infection, since, similar to TNF-α, increased IL-10 after treatment has significantly higher levels than those observed in the healthy group." (PMID 23824716, 2013). "UPEC induces IL-10 in the bladder during acute UTI, and this has been proposed to down-regulate inflammatory responses shortly after infection via monocytes/macrophages, and mast cells." (PMID 24155979, 2013). "In this infection model, CD4+ and CD8+ T cell derived IL-10 plays an essential role for the establishment of pathogen persistence." (PMID 24244162, 2013). "It is not possible, however, to quantitatively distinguish the importance of the early reduced IL-10 secretion from the likewise reduced IL-4 secretion and increased IFN-γ secretion following infection." (PMID 23825956, 2013). "IL-10+ APC have been shown to reduce the number of antichlamydial Th1 cells that develop and this results in a prolonged infection." (PMID 23365491, 2013). "In the protected 3-cure mice, significantly higher levels of plasma IL-10 and lower levels of IFN-γ than the others on day 7 post challenge infection were observed." (PMID 23724100, 2013). "Experimental infections in cattle with Neospora at mid gestation (Day 140 of gestation) have shown significant increases in IFN-γ, IL-10 and tumour necrosis factor (TNF) expression and Neospora-specific CMI and humoral responses in infected foetuses." (PMID 24090114, 2013).
infection (continued). "Therefore, although Brucella resistance to neutrophil killing has been well described, it is possible that the increased cytokine expression and pathology observed in IL10Rflox/LysMCre mice could also be due in part to a failure of neutrophils recruited to the site of infection to respond to IL-10." (PMID 23818855, 2013). "As expected, the infection induced IL-1, IL-6, KC, TNF-α, IL-10, IL-12, and IFN-γ release at all time points compared with noninfected mice." (PMID 23818746, 2013). "Our work demonstrates for the first time that IL-10 plays a detrimental effect to pulmonary PCM due to its suppressive effect on the innate and adaptive immunity resulting in progressive infection and precocious mortality of infected hosts." (PMID 24205424, 2013). "Thus, the levels and duration of IL-10 production are tightly regulated during the course of immune response against pathogens, while dysregulation in this process may result in prolonged/persistent infection and even systemic anergy to infected organisms." (PMID 23667643, 2013). "Remarkably, infection with Seui strain induced higher TNFα, CD80 and IL-10 expression than pN3 treated cells." (PMID 24070317, 2013). "A multiplexed bead assay was used to measure plasma levels of IL-5, IL-10, IL-12, IL-13, IFN-γ and TNF in BALB/c mice immunized against P. berghei K173 by repeated infection and drug cure before the first pregnancy." (PMID 24180253, 2013). "Both IL-10-producing CD5+ B cells and FoxP3+ TREG cells are stimulated by infection with schistosomes." (PMID 23429492, 2013). "The infection of J774A.1 macrophages resulted in an increase in TNF-α, IL-1β, and IL-6 expression; IL-10 was downregulated during Leishmania infection, although its expression recovered compared to noninfected macrophages." (PMID 23555077, 2013). "In the current study, we used these antibiotics to modify the community structure in the guts of IL10-/- C57BL/6 mice before and during infection with H. hepaticus, and then compared disease in treated and untreated mice as well as germfree mice." (PMID 24450737, 2013). "When cardiomyocytes were pre-incubated with IL-10 (20 ng/ml), Q-RT-PCR results showed a significant decrease in IL-6 and TNF-α mRNA levels after 4 h of infection." (PMID 24260222, 2013). "Gene expression studies have shown increased expression of IFNγ, IL12p40, Perforin, IDO, IL-4, IL-10, and forkhead box p3 (FOXP3) in infection and/or disease, with levels generally being highest if both were present." (PMID 23457650, 2013). "Infection of HCMV was found to induce the expression of different cytokines and chemokines among which were TNF-α, IL10, IL-8 and MCP-1." (PMID 23418456, 2013). "Thus, the relative contribution of each IL-10 producing cell type to the overall in vivo effects of this immunosuppressive cytokine is likely very complex and it might also differ depending on the tissue and the time of infection." (PMID 22876184, 2012). "On day 7 after infection, serum ALT levels had declined in both WT and IL-10−/− mice, although the levels in IL-10−/− mice remained elevated compared to WT levels." (PMID 22880122, 2012). "CD4+ T cells isolated on days 5 and 7 post-infection from α-CTLA-4-treated mice secreted significantly more IFN-γ and IL-10 than did CD4+ T cells from control mice." (PMID 22319445, 2012). "On the other hand, infection with MT forms result in an early production of IFN-γ, with subsequent control in the production of this cytokine by IL-10, which provided to these animals an immunomodulatory profile in the end of the acute phase." (PMID 22412949, 2012). "Several studies have shown that co-production of IL-10 by IFN-γ producing CD4+ Th1 cells is critically important for regulation of excessive Th1 and inflammatory responses in many infections." (PMID 22860150, 2012).
infection (continued). "Reversing the Treg cell recruitment and inhibiting their IL-10 production or blocking the IL-10 at the pathologic site(s) may constitute an effective intervention modality for repairing the immune deficit of VL patients and thereby contain the infection as well as improve the drug (SAG) response." (PMID 22347492, 2012). "The role that mammalian IL-10 plays in regulating anti-herpesvirus immunity in vivo has been elucidated in murine systems, particularly the murine cytomegalovirus (MCMV) model of infection." (PMID 23012619, 2012). "It has previously been shown that PBMC from blood donors produce high levels of IFN-γ concomitant with low levels of IL-10 after in vitro SEA stimulation, similar to what is observed during the acute phase of infection." (PMID 23270458, 2012). "Thus, it appears that T regulatory cell-derived IL-10 plays an important role in the suppression of immunological reactivity in the lung in the context of both allergic inflammation and infection, where it may help limit infection-related tissue damage." (PMID 22563306, 2012). "To further investigate the role of PAR-1 in the local inflammatory response, we determined levels of various cytokines (TNF-α, IL-6, IL-10, IL-12, IFN-γ) and chemokines (MCP-1, MIP-2) in lung homogenates at 6, 24 and 48 hours after infection." (PMID 23270594, 2012). "IL10 followed a similar pattern with a small delay while IL4 slowly increased and peaked 60 days post infection." (PMID 22253585, 2012). "A strong CD4+ proliferative T-cell response was observed at the early stage of infection, and IFN-γ, IL-2, and IL-5 were produced within the first weeks after infection whereas the detection of IL-10 was slightly delayed." (PMID 22400039, 2012). "The aim of this study was to characterize the in vivo plasma concentrations of the cytokines TNF-α, IFN-γ, IL-4, IL-10 and the overall role of CD4+ T cells in the development of cytokine levels during a primary infection." (PMID 22533922, 2012). "The infection of human THP1-derived macrophages by L. donovani in vitro suppresses TLR2 and TLR4-stimulated IL-12 release, with an increase in IL-10 production, through parasite-dependent contact." (PMID 22523644, 2012). "WT mice which received Stat1−/− bone marrow responded to infection with a systemic cytokine storm, i.e elevated serum levels of almost all measured cytokines and chemokines (IL6, IL22, TNFα, MCP1, IL10, Rantes, IP10 and MCP3)." (PMID 22719255, 2012). "Following the infection, IFNγ rapidly peaked after two time steps while IL4 and IL10 activation followed with a delay, in line with empirical findings." (PMID 22253585, 2012). "Our results show that CD4+ T cells from mice immunized with DnaK+Tul4+GPI responded to DnaK and Tul4 stimulation by producing IFN-γ, IL-10 and IL-17A; and both antigens are processed and presented to CD4+ and CD8+ T cells upon FT LVS infection." (PMID 23209745, 2012). "In attempts to focus more deeply on the impact of MT or BT infection on the T-cell cytokine pattern, we have characterized the frequency of TNF-α+, IFN-γ+ and IL-10+ T-cells as their major subsets (CD4+ and CD8+) within splenocytes." (PMID 22412949, 2012). "On day 5 after infection, WT mice exhibited reduced liver PAS staining, though this reduction in positive PAS staining was markedly more apparent in IL-10−/− mice." (PMID 22880122, 2012). "IL-27 plays a role in the development of IFNγ+IL-10+ CD4+ T cells during experimental L. major and Listeria monocytogenes infection in vivo, as assessed using IL-27Rα−/− mice." (PMID 22911108, 2012). "At high multiplicities of infection (10 MOI), RAW cells up- regulated cell surface expression of TLR4 and secreted significant amounts of TNF-α, MCP-1, IL-10 and IL-12 and NO." (PMID 22642811, 2012). "The expression of the anti-inflammatory cytokine IL-10 (85.91 ± 33.96 fold, P = 0.0357) was increased 10 days after CVB3 infection and decreased to a normal expression level 28 days after infection." (PMID 22675647, 2012).
infection (continued). "After 6 months post-infection, cytokine analyses in these mice showed a persistent IFN-γ production regulated by an IL-10-rich immune response, which is compatible with a protective therapeutic effect in B10.A mice." (PMID 22389734, 2012). "The conclusion from those analyses is that the combination of increased IL-10 and IP-10 with decreased RANTES levels was most predictive of infection." (PMID 23155405, 2012). "Four animals were sacrificed 2, 4, 7, 10, 16, and 21 days after infection to obtain the serum for cytokines quantification (TNF, IFNγ, and IL-10)." (PMID 22666132, 2012). "The earliest immune response to the infection was observed in the head kidney, with IFN-γ, IL-10 and MHC-I being significantly up-regulated at 2 wpi indicating a pro-inflammatory response." (PMID 23116479, 2012). "Conversely, upon initial infection, BM-induced an inflammatory suppressor, IL-10, from ATII cells and macrophages with delayed secretion of inflammatory cytokines via TLR4 at 20 h post-infection." (PMID 23293773, 2012). "Peritoneal and splenic macrophages and dendritic cells produce IL-10 after MCMV infection and it is known that monocyte/macrophages accumulate in the liver during infection." (PMID 22880122, 2012). "The kinetics of production of the anti-inflammatory IL-10 differed significantly in animals infected with the four strains with a peak at day 1 in animals infected with LUH8326, at day 2 after infection with RUH134 and at day 3 after infection with LUH5875." (PMID 22347396, 2012). "If antigen-specific memory T or B cells are involved, this IL-10 production may reflect the acquisition of tolerance to schistosome antigens resulting from exposure in utero, with long-term implications for the response of such children on exposure to infection." (PMID 21888656, 2011). "Seven days after infection, both groups administered L. casei CRL 431 decreased the number of IL-10 (+) cells to values similar to C group." (PMID 21813005, 2011). "While e.g. IL12B expression was increased right after infection and throughout the entire experiment, IL10 and IL12A showed lower expression in early infection stage compared to E. coli K12 stimulated MDMs (P<0.005, unpaired t test)." (PMID 21629653, 2011). "Thus, IL-10 may play a critical role in maintaining lung function during infection." (PMID 21829368, 2011). "Twelve weeks post-infection, the expression levels of IFN-γ, IL-4, IL-10, TNF-α and Arg I were similar in both groups." (PMID 21390155, 2011). "When comparing PBMCs obtained from children undergoing infection from each ethnic group, the IFN-γ/IL-10 ratio was significantly higher in Fulani than in Dogon upon stimulation with TLR4 and TLR9 ligands (p = 0.002 and p = 0.0051; respectively)." (PMID 21483827, 2011). "IL-10-blockade during PZQ treatment further increased anti-worm immune responses, and afforded significant protection from re-infection." (PMID 21829367, 2011). "To clarify the role of IL-10 in infected chicken embryos, we applied 100 ng recombinant chicken IL-10 onto the CAM of 10 days old eggs 15 min prior to infection." (PMID 21603634, 2011). "The production of IL-1β, IFN-α, IL-10, TGF-β, IL-4 and TNF-α by the nervous tissues of infected animals increased significantly at different times after infection." (PMID 21813860, 2011). "Prior to infection protectively vaccinated mice exhibit augmented CD4 and CD8 IFNγ and memory responses as well as decreased IL-10 and IL-13 responses." (PMID 21695103, 2011). "Two or five days after MAb treatment (day 6 or 9 after infection), serum was harvested and levels of relevant cytokines (IFN-γ, TNF-α, IL-10, IL-12 p40, IL-17, and IL-18) were measured by bioplex assay." (PMID 22144897, 2011). "We also investigated the kinetics of accumulation of IL-10-expressing cells in the lungs following RSV infection and found that the IL-10-expressing cells were restricted to the acute phase of infection." (PMID 21829368, 2011).